TIMP3 (TIMP metallopeptidase inhibitor 3)
Diseases named in the same sentence as TIMP3 in open-access papers (continued):
Sharing a sentence is not in itself a finding about the gene and the disease.
lung cancer (continued). "Additionally, we evaluated the expression of ALKBH5 target mRNAs CDKN1A and TIMP3 in lung cancer using the TCGA dataset." (PMID 35318440, 2022). "This evidence corresponds to our study where highly expressed FOXF1 could inhibit cell migration in lung cancer, possibly through upregulation of E-cadherin and TIMP3." (PMID 32370197, 2020). "Moreover, in the lung cancer patient tissue, the expression of IL-32 and TIMP-3 was dramatically decreased at a grade-dependent manner compared to normal lung tissue." (PMID 29467412, 2018). "We also determined the effect of IL-32γ on the TIMP-3 methylation in lung cancer cell lines." (PMID 29467412, 2018). "To further investigate whether the increase of TIMP-3 expression has an inhibitory effect on lung cancer cell growth through decreasing methylation of TIMP-3, IL-32γ transfected lung cancer, we determined the expression of TIMP-3 and its methylation in lung cancer." (PMID 29467412, 2018). "We further identified the effect of other isoforms of IL-32, including IL-32α and IL-32β, on TIMP-3 promoter methylation in A549 and NCIH460 lung cancer cell lines." (PMID 29467412, 2018). "Both miR-221 (highly expressed in the proestrus stage of females exposed to O3) and miR-222 (upregulated in males exposed to O3) are involved in the development and progression of lung cancer by targeting the tumor suppressor genes PTEN and TIMP3." (PMID 29739446, 2018). "In accordance with patient tissue and animal tissue, TIMP-3 expression was increased by the introduction of IL-32γ plasmid in LLC, A549 and NCIH460 lung cancer cell lines." (PMID 29467412, 2018). "Previous studies showed similar results on TIMP‐3 regulation which is induced by ERK phosphorylation and the downstream transcriptional factor, Sp1 in human lung cancer cells." (PMID 28672103, 2017). "IL-32γ reduces lung cancer cell growth in vitro and in vivo by inhibiting the binding of NFκB-dependent DNA (cytosine-5)-methyltransferase 1 (DNMT1) to TIMP3 promoter and thus increased TIMP3 expression contributes to the inhibition of cancer growth." (PMID 38542164, 2024). "Moreover, we also investigated the effect of NF-κB activation on TIMP-3 methylation and expression of DNMT expression in the lung cancer cells (A549 cells) treated with recombinant protein p50." (PMID 29467412, 2018). "First, we determined the methylated TIMP-3 and unmethylated TIMP-3 in lung cancer cell lines." (PMID 29467412, 2018). "TRAIL (TNF-related apoptosis inducing Ligand) is a member of the TNF family involved in programmed cell death in cancer cells, and miR-221, miR-222 were found to guide lung cancer resistance to TRAIL therapy by downregulating PTEN and TIMP3, which are both tumor suppressors." (PMID 25593996, 2014). "However, additional targets of miRNAs 221-222, such as PTEN/TIMP3 and PUMA (also known as Bcl-2 binding component 3), seem to mediate TRAIL resistance, migration and invasiveness, thus correlating with the frequent overexpression of these miRNAs in epithelial cancers, including lung cancers." (PMID 25593996, 2014).
colorectal cancer (22 papers, 1997 to 2025). A primary or metastatic malignant neoplasm that affects the colon or rectum. "Gene interaction networks elucidated that TIMP3 and its associated genes play a pivotal role in cancer progression, particularly in processes critical to colorectal cancer, such as extracellular matrix organization and angiogenesis." (PMID 41009435, 2025). "Banday and Sameer demonstrated that the TIMP3-1296T/C promoter SNPs was associated with decreased risk of colorectal cancer in ethnic Kashmiri population." (PMID 33725949, 2021). "TIMP-3 expression is associated with favorable prognoses in various cancers such as colorectal cancer, liver cancer, and NSCLC." (PMID 33126605, 2020). "The females carrying the variant allele, TIMP3-1296C in heterozygous form (TC) or variant homozygous form (CC) were at a decreased risk of developing colorectal cancer in comparison with males." (PMID 30988064, 2019). "The variant genotype (CC) of TIMP3-1296T/C SNP was also significantly associated with a decreased risk of colorectal cancer [OR, 0.18 (95%CI, 0.05–0.65); P=0.009]." (PMID 30988064, 2019). "In the present study, we systematically evaluated the possible association between TIMP2-418G/C and TIMP3-1296T/C SNPs and susceptibility to colorectal cancer in Kashmiri population through a case–control setup." (PMID 30988064, 2019). "Further, the less common TIMP3-1296C allele showed an overall significant association with colorectal cancer (P=0.0001)." (PMID 30988064, 2019). "The TIMP3-1296C allele was associated with a decreased risk of colorectal cancer [OR, 0.50 (95%CI, 0.35–0.71); P=0.0002]." (PMID 30988064, 2019). "The heterozygous genotype (TC), variant genotype (CC), less common TIMP3-1296C allele and combined variant genotype (TC + CC) all were significantly associated with a decreased risk of colorectal cancer." (PMID 30988064, 2019). "In this study, we found that TIMP3 expression is associated with positive prognosis of colorectal cancer (CRC) clinicopathologically." (PMID 31588243, 2019). "The overall association between the TIMP3-1296T/C SNP and the modulation of colorectal cancer risk was found to be highly significant (P=0.000)." (PMID 30988064, 2019). "The study subjects aged ≤50 years and carrying the variant allele, TIMP3-1296C in the heterozygous form (TC) or variant homozygous form (CC) were at a decreased risk of developing colorectal cancer." (PMID 30988064, 2019). "In the present study, we investigated the role of functional TIMP2-418G/C and TIMP3-1296T/CSNPs in the promoter region of TIMP2 and TIMP3 genes, respectively, as a potential colorectal cancer risk factor in a case–control study design with 142 case subjects and 184 control subjects." (PMID 30988064, 2019). "We also looked into the possibility that patient survival in colorectal cancer was related to variations in the TIMP3 gene." (PMID 41009435, 2025). "We analyzed the CRC_EMTAB8107, CRC_GSE146771, CRC_GSE166555 and CRC_GSE179784 colorectal cancer datasets to investigate TIMP3 expression across different cell populations within the TME." (PMID 41009435, 2025). "In colorectal cancer (especially rectal cancer), patients with high-cytoplasmic-staining levels of TIMP3 have a comparatively high 5-year survival rate." (PMID 38542164, 2024). "CircFNDC3B, a circular RNA that sequesters miR-937-5p, leads to elevated expression levels of TIMP3 and inhibits mouse colorectal cancer progression." (PMID 38542164, 2024). "CircFNDC3B serves as a sponge of miR-937-5p to regulate TIMP3 expression and in colorectal cancer development." (PMID 34434890, 2021). "Herein, we found that TIMP3 expression correlated clinical pathologically with colorectal cancer patient, which urged us to develop TIMP3 inducers as therapeutic agents for colorectal cancer treatment." (PMID 31588243, 2019).
colorectal cancer (continued). "Based on Duke's classification of colorectal cancer cell lines, TIMP3 is expressed abundantly in normal cells, whereas malignant CRC cells are correlated to disease stage progression." (PMID 31588243, 2019). "In colorectal carcinoma, knockout of both DNMT1 and DNMT3B caused promoter demethylation of TIMP3, thus increasing the TIMP3 mRNA level." (PMID 31624299, 2019). "For example, adenovirally transferred TIMP3 reduces adhesion, migration, and invasion behaviors in colorectal cancer cells and suppressed tumor growth in vivo." (PMID 27058897, 2016). "In contrast, TIMP-3 mRNA is localized to stromal fibroblast-like cells in colorectal carcinomas, with an increased incidence in moderately and poorly differentiated groups compared with well-differentiated carcinomas." (PMID 9184186, 1997). "Therefore, we developed a series of arylsulfonamide derivatives as TIMP3 inducers in order to define potential colorectal cancer therapeutic agent." (PMID 31588243, 2019). "The non/never-smoking study subjects carrying the variant allele, TIMP3-1296C in heterozygous form (TC) or variant homozygous form (CC) were at a decreased risk of developing colorectal cancer." (PMID 30988064, 2019). "Indeed, studies have shown that adenovirally delivered TIMP3 overexpression reduced blood vessel density, promoted apoptosis and significantly reduced tumor growth in melanoma in vivo model 5 and suppressed malignant behaviors such as migration, invasion and tumor growth of colorectal cancer cells." (PMID 31588243, 2019). "With all aspects considered, this work bridges the gap between immune response and gene expression in colorectal cancer (CRC), expanding our knowledge of TIMP3 as a tumor suppressor and immune landscape regulator with potential implications for immunotherapeutic targeting." (PMID 41009435, 2025). "This also suggests that TIMP3 plays an important role in tumor metastasis rather than colorectal cancer survival." (PMID 31588243, 2019). "In comparison to the equivalent normal tissues, TIMP3 was significantly reduced in various cancer types, including lung adenocarcinoma (LUAD), kidney chromophobe (KICH), lung squamous cell carcinoma (LUSC), colorectal cancer (CRC), and uterine carcinosarcoma (UCS) tissues." (PMID 41009435, 2025). "Metastatic abilities of SW620 colorectal cancer cells were also suppressed by Rh1 (100 μM) via inhibition of MAPK signaling transduction pathways and transcriptions of MMP-1 and MMP-3 while increasing expression of tissue inhibitor of metalloproteinases 3 (TIMP3), a negative regulator of MMPs." (PMID 33671187, 2021). "Due to the absence of clinical cohorts of colorectal cancer (CRC) patients undergoing immunotherapy, TIMP3’s role in predicting immunological responses in CRC could not be evaluated." (PMID 41009435, 2025). "Target genes of the mature miRNA sequence have not been fully characterized, but colorectal cancer appears to promote tumorigenesis through targeting of CCAAT/enhancer binding protein beta and tumour invasion by directly targeting tissue inhibitors of metalloprotease 3 (TIMP3)." (PMID 29914173, 2018).
osteoarthritis (20 papers, 2016 to 2026). A noninflammatory degenerative joint disease occurring chiefly in older persons, characterized by degeneration of the articular cartilage, hypertrophy of bone at the margins and changes in the synovial membrane. "Because these enzymes play key roles in articular cartilage turnover, TIMP-3-mediated inhibition protects against cartilage degradation, a hallmark of osteoarthritis (OA), and has been explored as a therapeutic target." (PMID 41909687, 2026). "The balance of ADAMTS4 and TIMP3 levels is crucial in the development of osteoarthritis, in which the overactivation of ADAMTS4 is implicated in its pathogenesis." (PMID 36721026, 2023). "In this study, we evaluated the effect of the CXCL12/CXCR4 axis on TIMP-3 expression in rats with post-traumatic osteoarthritis (PTOA) and explored the underlying mechanism(s)." (PMID 32038242, 2019). "Metformin also led to an increased expression of TIMP1 and TIMP3 in osteoarthritis chondrocytes co-cultured with metformin-treated adipose tissue-derived human mesenchymal stem cells." (PMID 37313172, 2023). "A cyclic peptide derived from TIMP3 (61EASESLAG70 enclosed by a Cys at each end) targeting ADAMTS4 has been explored as a treatment for osteoarthritis, further investigation is required for its potential usage in patients." (PMID 32612540, 2020). "There was sufficient protease activity in synovial fluid from human joints with osteoarthritis to release TIMP‐3 from the LAP fusion." (PMID 30450736, 2019). "Suramin is thus a promising scaffold for the development of novel therapeutics to increase TIMP-3 levels and inhibit cartilage degradation in osteoarthritis." (PMID 28798097, 2017). "In the context of osteoarthritis, both the collagenase MMP-13 and the aggrecanases ADAMTS-4 and ADAMTS-5 are susceptible to such ECM-mediated increase in TIMP-3 potency." (PMID 27582494, 2016). "Timp3-null mice show increased collagenase and aggrecanase activity in cartilage and increased spontaneous osteoarthritis with age." (PMID 27582494, 2016). "Treatment with recombinant TIMP-3 has been shown to block cartilage degradation in vitro and in in vivo models of osteoarthritis, further illustrating the chondroprotective activity of TIMP-3." (PMID 27582494, 2016). "Because cartilage erosion is a common pathological alteration in OA, targeting some key metalloproteinases such as MMP-3, ADAMTS-5 besides their inhibitor TIMP-3 by natural products, could be an effective strategy to protect against osteoarthritis." (PMID 37259405, 2023). "These mutants or small molecule inhibitors of TIMP-3 endocytosis may be of use in osteoarthritis as well as in other pathological conditions characterized by excess, dysregulated metalloproteinase activity, such as cancer and chronic diabetic wounds." (PMID 27582494, 2016). "The use of recombinant TIMP-3 has been shown to inhibit cartilage degradation both in vitro and in vivo, confirming TIMP-3 chondroprotective activity under osteoarthritis conditions." (PMID 36013323, 2022). "TIMP-3 has been proven beneficial in diseases such as rheumatoid arthritis, which is majorly driven by an excess activity of TIMP-3 target ADAM17, and osteoarthritis, which is characterized by cartilage breakdown due to ADAMTS-4 and -5." (PMID 36013323, 2022). "Thanks to its broader inhibitory profile, TIMP-3 has been proven beneficial in diseases such as rheumatoid arthritis, which is majorly driven by an excess activity of TIMP-3 target ADAM17, and osteoarthritis, which is characterized by cartilage breakdown due to ADAMTS-4 and -5." (PMID 36013323, 2022). "In the field of orthopedics, DHEA has been shown to exert beneficial effects on osteoarthritis-damaged cartilage by actively regulating the balance of anabolic and catabolic factors (e.g., MMPs/TIMP-1 and ADAMTS/TIMP-3) and inhibiting catabolic signaling pathways (e.g., Wnt/β-catenin)." (PMID 34090401, 2021).
osteoarthritis (continued). "We evaluated expression of CXCL12/CXCR4 and TIMP-3 in the knee joints of rats with and without osteoarthritis (OA) by immunohistochemistry, immunofluorescence, Western blotting, and enzyme-linked immunosorbent assay (ELISA)." (PMID 32038242, 2019).
colon cancer (19 papers, 2013 to 2025). "It was also proven to cause DNMT1 proteosomal degradation in colon cancer cells and to demethylate and reactivate TIMP3, MLH1 and P16 promoters in HCT116 cells." (PMID 28067760, 2017). "In colon cancer cells growing in the liver, cyclin-dependent kinase 8 reduces TIMP3 expression by inducing miR-181b." (PMID 38542164, 2024). "Another aryl sulfonamide-based derivative, MPT0B390, transcriptionally upregulates TIMP3 levels in colon cancer cell lines and HUVEC by inhibiting the expression of the enhancer of zest homolog 2 (EZH2, a histone methyltransferase)." (PMID 38542164, 2024). "Among the most significant upregulated genes were plakophilin-2 (PKP2), which has been described as a Wnt/β-catenin target in colon cancer CAFs, and TIMP metallopeptidase inhibitor 3 (TIMP3), which was also highly upregulated in ovarian cancer CAFs." (PMID 39567960, 2024). "According to a recent research, BC032913 plays an inhibitory role in colon cancer aggression by upregulating TIMP3 through inactivation of the Wnt/β-catenin pathway." (PMID 33744851, 2021). "In the colon cancer cells, the protein level of TIMP3 was also increased with the miR-4435 inhibitor treatment compared to non-treatment." (PMID 32071343, 2020). "Overexpression of TIMP3 was indicated to inhibit cell proliferation and migration in colon cancer, melanoma and other human cancers." (PMID 32896063, 2020). "Dysregulated expression of TIMP3 was observed in clear cell renal cell carcinoma, breast cancer and colon cancer." (PMID 32896063, 2020). "We also validated the increased levels of MMPs and TIMP3 proteins in colon cancer cells compared to normal cells." (PMID 32171282, 2020). "It has been reported that TSA can activate certain hypermethylated genes, including CDKN2B, CDKN2A, MLH1 and TIMP3 in colon cancer cells after Dnmt1 inhibition by DNA demethylating agent such as 5-aza-dc." (PMID 32334468, 2020). "TIMP3 has been reported to induce apoptosis and inhibit growth and proliferation in certain colon cancer cell lines." (PMID 30988064, 2019). "The hsa-miR-181 family has been shown to be deregulated also in other solid tumours such pancreas, prostate, gastric and colon cancers and was able to target tumour suppressors, including TIMP3, CYLD, PTEN and p27." (PMID 26672991, 2015). "In colon cancer cell lines, TIMP-3 suppresses neoplasia by inducing apoptosis, an action thought to be mediated by stabilization of TNF-α receptors." (PMID 24518611, 2014). "In vitro data also revealed that increasing TIMP-3 levels reduced adhesion, migration and invasiveness of a human colon cancer cell line, while in vivo studies revealed that TIMP-3 transduction reduces both tumor growth and liver metastasis." (PMID 24518611, 2014). "Following an analysis of TIMP3 expression and its prognostic implications in COAD patients, using LinkedOmics, we identified co-expressed genes and associated pathways to explore its potential biological roles in colon cancer." (PMID 41009435, 2025). "The aberrant expression of matrix metalloproteinase-3 (MMP-3) and tissue inhibitor of metalloproteinase-3 (TIMP-3) is potentially associated with metastasis in several carcinomas such as NPC, cervical cancer, breast cancer, lung cancer, and colon cancer." (PMID 37037466, 2023). "Metallopeptidase (MMP) 9 and 12 and TIMP3 were increased in the colon cancer cells." (PMID 34827210, 2021). "In addition, miR-4435 inhibitor was transfected into mutant UQCRB-expressing cell lines and colon cancer cells to validate TIMP3 as a target of miR-4435 further." (PMID 32071343, 2020). "Further, TIMP3 has been reported to inhibit tumor growth, angiogenesis, invasion, and metastasis and promote apoptosis and same has been reported in vitro in human colon cancer cell lines." (PMID 30988064, 2019). "Moreover, restoring TIMP-3 levels induces colon cancer cell death and limits cell proliferation." (PMID 36555545, 2022).
colon cancer (continued). "However, MMP9, MMP12 and TIMP3 proteins were increased in colon cancer cells." (PMID 32171282, 2020). "MPT0G013, an arylsulfonamide-based derivative, upregulates TIMP3 in HUVEC and colon cancer cells in mouse xenograft models." (PMID 38542164, 2024). "By upregulating TIMP3 expression, MPT0G013 and MPT0B390 suppress the proliferation and metastasis of colon cancer tumours in vitro and in vivo." (PMID 38542164, 2024). "Given abnormal levels of MMP9, MMP12 and TIMP3 mRNA expression in tumors from CRC patients and controls, we next measured the level of the MMPs and TIMP3 proteins in human colon cancer epithelial cells compared to normal colon cells by immunoblot." (PMID 32171282, 2020). "It was shown to reactivate TSGs, such as P16, TIMP3 and SFRP1, in the colon cancer cell line HCT116 by promoter demethylation." (PMID 28067760, 2017). "Furthermore, it has been indicated that 5-Aza-CdR demethylates the promoter sequence of TIMP-3 and p16 in HCT116 colon cancer." (PMID 34466608, 2020). "Colon cancer epithelial cells had higher levels of TIMP3 protein than normal colon epithelial cells." (PMID 32171282, 2020).